KLF6 (KLF transcription factor 6)
Diseases named in the same sentence as KLF6 in open-access papers (continued):
Sharing a sentence is not in itself a finding about the gene and the disease.
tumor (continued). "To elucidate the mechanism by which TAM-derived PGE2 controls UHRF1 expression, we have demonstrated that PGE2 promoted the dissociation of KLF6, a transcription factor and a tumor suppressor, from the miR-520d promoter, thereby decreasing miR-520d level." (PMID 35664070, 2022). "While wild-type KLF6 reduces tumor growth and progression in general, several tumor-derived KLF6 mutations and alternatively spliced variants boost proliferation and tumorigenicity." (PMID 35345512, 2022). "Low KLF6 expression was linked to a poorer prognosis for OS time in patients with CRC in our study, showing that KLF6 works as a tumor suppressor, which is consistent with earlier findings." (PMID 35345512, 2022). "KLF6 was related to many biological pathways as a tumor-suppressive gene in various types of cancer." (PMID 35112985, 2022). "The data suggest an interaction between KLF6 and tumor miR-520d in the context of PGE2 biological activity in HCC." (PMID 35664070, 2022). "In consequence, upregulated UHRF1 methylates H3K9 to diminish tumor KLF6 expression, a tumor inhibitory transcriptional factor that directly transcribes miR-520d." (PMID 35664070, 2022). "KLF6, a zinc finger transcription factor, is a tumor suppressor that controls cell proliferation, differentiation, and migration." (PMID 35664070, 2022). "KLF6 was reported to be a suppressor gene of tumor in prostate cancer, colorectal cancer, and hepatocellular carcinoma." (PMID 35112985, 2022). "We demonstrated that TAM-derived PGE2 stimulated tumor UHRF1 expression via blocking miR-520d expression, loss of miR-520d expression led HCC progression via tumor UHRF1, and tumor UHRF1 targeted tumor repressor KLF6." (PMID 35664070, 2022). "Further studies have revealed that knockdown KLF6 had positive effects on tumor progression, while KLF6 overexpression resulted in decreased tumorigenicity." (PMID 36615000, 2022). "Again, overexpression of UHRF1 and KLF6, respectively, increased and decreased tumor colony formation and sphere formation." (PMID 35664070, 2022). "KLF6 is a ubiquitously expressed molecule that regulates growth arrest and functions as a tumor suppressor." (PMID 36499521, 2022). "The expression levels of ZFAS1 and KLF6 were both significantly elevated, while the expression of miR-190a-3p was inhibited in CC tumor tissues." (PMID 35112985, 2022). "Labelled by benign signatures, subclusters 1 and 2 similarly overexpressed metabolism‐related genes and tumour suppressors (KLF6, EGR1, GC, FAM46A, ZFP36, BTG2, etc.)." (PMID 35075805, 2022). "Knockdown of MIR4435-2HG inhibited proliferation, metastasis and tumour progression by downregulating Kruppel like factor 6 (KLF6) as the direct target of miR-513a-5p." (PMID 35715800, 2022). "In another study, the knockdown of XIST induced the conversion of M1 to M2 by inhibiting the expression of enhancer binding protein (C/EBP) α and Kruppel-like factor 6 (KLF6), thereby promoting the proliferation and migration of tumor cells." (PMID 35222443, 2022). "Here, we found that the expression levels of ZFAS1 and KLF6 were elevated, while the expression of miR-190a-3p was inhibited in CC tumor tissues." (PMID 35112985, 2022). "KLF6 is considered a tumor suppressor in various tumors and acts by upregulating p21 and downregulating B-cell lymphoma 2 (BCL-2)." (PMID 36499521, 2022). "The mRNA expression and protein expressions of KLF6 and p21 were significantly augmented in the C3G treatment group in comparison with normal group, representing the vital role of KLF6 in the tumor xenograft inhibition in vivo." (PMID 35406634, 2022). "Growing evidence proved that KLF6 acts as a tumor suppressor molecular in multiple malignant cancers." (PMID 34078414, 2021). "As one crucial tumor suppressor, KLF6 has been found to bind to the promoter region of SP1 and reduce its expression in HCC21." (PMID 33431838, 2021).
tumor (continued). "In summary, these evidences manifested that the repression of KLF6 was indispensable for the tumor-promoting effect of SNHG6." (PMID 33431838, 2021). "Kruppel-like factor 6 (KLF6) is a member of the Kruppel-like factor family and is considered a tumor suppressor." (PMID 34776953, 2021). "In recent years, with advances in the understanding of tumor pathogenesis, researchers have found that the inactivation of KLF6 plays an increasingly important role in promoting tumor production." (PMID 33816511, 2021). "The ratio between SV1 and wild-type KLF6 was increased in HCV-associated HCC, which was related to higher tumor aggressiveness." (PMID 35008179, 2021). "It has been proved that KLF6 plays the role of tumor suppressor in various tumors by regulating diverse biological processes." (PMID 34776953, 2021). "Transcripts of well-established tumor suppressor genes (Klf6, CD82) and positive regulators of apoptosis (Pmaip1) were found to be suppressed in Eμ-TCL1;CXCR4C1013G." (PMID 34363012, 2021). "Third, KLF6 was not only reported to be a tumor regulator but also an immune/inflammation trigger; therefore, the involvement of lnc-KASRT and KLF6 in the tumor immune microenvironment is another hotspot for further research." (PMID 34568030, 2021). "Crosstalk between Leptin and Notch signaling regulated the expression of miR343-3p, which inhibited tumor suppressor, KLF6 thereby affecting the chemosensitivity." (PMID 33968932, 2021). "KLF6 often exerts a tumor suppressor effect in cells, and its abnormal expression leads to abnormal cell growth and malignant proliferation." (PMID 33955459, 2021). "Platelet-derived TGF-β downregulates the tumor suppressor gene KLF6, leading to enhanced tumor cell proliferation and cell cycle progression in vitro as well as enhanced tumor cell growth in vivo." (PMID 33803718, 2021). "Meanwhile, within the SRSF1 intronic region, UCR-419 (named lnc-KASRT) fits the definition of a lncRNA and regulates KLF6 (a common tumor regulator) alternative splicing by sponging the SRSF1 gene." (PMID 34568030, 2021). "That is, on the one hand, siRNA-mediated inhibition of KLF6-SV1can up-regulate the pro-apoptotic protein Noxa and reduce anti-apoptotic proteins, thus accelerating the apoptosis of tumor cells." (PMID 33816511, 2021). "We also noted that some proliferation-associated genes in tumor cells were also significantly regulated by CRNDE knockdown, including IGFBP4, ANXA1, KLF6, AATF, and IFI16." (PMID 33298855, 2020). "In cancers where pro-oncogenic KLF6-SV1 supports tumorigenesis, primarily by antagonising the tumour-suppressor full-length KLF6, depleting this KLF6-SV1 isoform seems an attractive option." (PMID 32998281, 2020). "It lacks all three zinc finger DBDs, leading to the expression of a mislocalized cytoplasmic isoform, which has opposite effects on cell proliferation, invasion, apoptosis and tumor dissemination compared to KLF6." (PMID 32244895, 2020). "Contrary to its widely reported role as a tumour suppressor, there were several studies that reported the growth-promoting functions of KLF6 in cancer." (PMID 32998281, 2020).
tumor (continued). "In HCC Hep3B and HepG2 cells, elevated miR-191 was sponged by has-circ-0000204, and the expression of tumor suppressor KLF6 increased via binding reduction of miR-191 to the 3′UTR region of KLF6 mRNA." (PMID 32937886, 2020). "Consistent with the previous results, immunochemistry analysis confirmed that KLF6 proliferation index in sh‐MIR4435‐2HG+pcDNA3.1‐xenografted tumours was weaker than that in sh‐NC+pcDNA3.1‐xenografted tumours." (PMID 33460239, 2020). "The full-length KLF6 acts as a tumor suppressor in a variety of cancers, including prostate, hepatocellular, colorectal, gastric, lung, head and neck, ovarian and brain cancers." (PMID 32244895, 2020). "Using real-time PCR and western blot assays for further verification, we found that KLF6, which is known as a tumor suppressor that induces apoptosis in various cancer cells, was upregulated in both RNA and protein expression after ART treatment." (PMID 31723124, 2019). "The presumed role of KLF6 as tumor suppressor comes from its ability to reduce cell proliferation through different cellular mechanisms as the regulation of cell cycle components, oncogene signaling and apoptosis." (PMID 31824948, 2019). "Collectively, these data suggest that HIF2A supports KLF6 expression by acting through the large KLF6 super enhancer, potentially explaining the relatively high KLF6 levels in ccRCC when compared to other tumour types." (PMID 30858363, 2019). "We report the identification of a cellular signalling loop that links the transcription factor KLF6 to lipid metabolic activity, enhanced tumour growth and metastatic colonization in ccRCC." (PMID 30858363, 2019). "Among these altered genes, some oncogenes, such as PON2 and CD34, were downregulated, and some tumor suppressors, such as KLF6 and JUN were upregulated." (PMID 31723124, 2019). "Genetic analysis revealed selection for the wildtype KLF6 gene in KLF6-targeted tumours when compared to the same cells in tissue culture, indicating that the tumours formed by KLF6-targeted cells consisted at least partially of escaper cells." (PMID 30858363, 2019). "In murine xenotransplantation models of RB, we further confirmed that ART inhibits RB tumor growth, induces tumor cell apoptosis and upregulates KLF6 expression." (PMID 31723124, 2019). "To further verify that KLF6 plays a crucial role in ART-induced RB tumor growth, we constructed subcutaneous RB models and intraperitoneal injected with ART (50 mg/kg) or saline for 2 weeks." (PMID 31723124, 2019). "KLF6, a zinc finger transcription factor, is a tumor suppressor and plays an important role in the development and metastasis of various human cancers." (PMID 31723124, 2019). "One of the members of this family is the Krüppel-like factor 6 gene (KLF6), Changing the expression of this tumor suppressor gene plays a role in the incidence of cancer." (PMID 31724937, 2019). "Wild-type KLF6 (wtKLF6) is a tumor-suppressor gene frequently inactivated in colorectal, prostate, colon cancers as well as in astrocytic gliomas." (PMID 29432497, 2018). "Another part of our study is concerned with the copy number variation of the KLF6 gene in tumor tissues versus normal nasopharyngeal mucosae." (PMID 29854578, 2018). "Knockdown of full length KLF6 increased tumour formation whereas knockdown of KLF-SV1 inhibited tumour formation." (PMID 29693622, 2018). "Our results showed that the wild-type isoform of KLF6 (wtKLF6) is significantly downexpressed in tumor tissues compared to normal nasopharyngeal mucosa." (PMID 29854578, 2018). "It was reported that KLF2 and KLF6 act as tumor suppressor genes, and downregulation of KLF2 or KLF6 was associated with poor survival in several cancers." (PMID 29290960, 2017).
tumor (continued). "Ectopic expression of KLF6-wt attenuated tumor growth as evidenced by reduced bioluminescence imaging (BLI analysis) 3 weeks after cell injection (P=0.001, t-test)." (PMID 28166199, 2017). "Among several mechanisms of tumor suppression, KLF6 inhibits cell cycle progression and proliferation." (PMID 28808340, 2017). "KLF6 is known as a tumor suppressor gene, and its frequent down-regulation has been implicated in several human cancers." (PMID 28638139, 2017). "The transcription factor KLF6 gene has been identified as a tumor suppressor because of its inactivation in several types of cancers." (PMID 28881705, 2017). "As a consequence, it is concluded that C3G activity on tumor growth inhibition was probably through KLF6-mediated p21 induction, by disruption of the Cyclin D1 and CDK4 interaction, thus blocking the cell cycle." (PMID 27690088, 2016). "KLF6 plays a crucial role in tumor suppression by modulating the expression of a broad range of genes governing biological functions associated with cell growth, differentiation, adhesion and endothelial motility." (PMID 27057625, 2016). "Our results indicate that KLF6 functions as a tumor suppressor and inhibits migration and invasion of HCC cells." (PMID 27057625, 2016). "Recently, a unique mechanism of KLF6 inactivation has been identified wherein alternatively spliced isoforms of KLF6 are generated that antagonize the tumor suppressive functions of the full-length, wtKLF6 protein." (PMID 27057625, 2016). "qPCR screening showed that C3G treatment up-regulated the expression of the KLF6 gene, which is an important tumor suppressor gene inactivated in many human cancers." (PMID 27690088, 2016). "We also compared tumor metastasis to important organs in these groups and were surprised to find that KLF6 overexpression resulted in obvious inhibition of distant metastasis to lung, omentum and mesenterium around stomach and small intestine." (PMID 27057625, 2016). "KLF6 isoforms were also found to be involved in tumor progression, and the activity of AJUBA was found to promote cancer growth." (PMID 27902686, 2016). "Overexpression of KLF6 significantly suppressed tumor growth and metastasis in a mouse model of HCC metastasis, indicating the therapeutic potential of KLF6 in HCC metastasis." (PMID 27057625, 2016). "KLF6 and p21 protein levels were significantly increased, indicating the critical role of KLF6 in the tumor xenograft suppression in vivo." (PMID 27690088, 2016). "Klf6 has been characterized as a tumor suppressor in prostate, ovary, liver, and gut, and Klf4, Klf5, and Klf6 are also implicated as regulators of viability." (PMID 27213272, 2016). "Tumor derived KLF6 mutants and alternatively spliced isoforms promote tumorigenesis and they potentiate oncogenic WNT signalling." (PMID 25781993, 2015). "The tumor suppressor function of KLF6 was further demonstrated in hepatic and gastric cancer and linked to a role in cellular differentiation." (PMID 24429391, 2014). "Since KLF6 is thought to be a tumor suppressor, we used several established cancerogenic and tumorigenic fly models to test if luna was able to ameliorate or modulate these effects." (PMID 24915236, 2014). "It has been shown that KLF6 suppresses tumor growth through activating protein 21 wild-type activated fragment 1/cyclin inhibitor protein 1 (p21 WAF1/Cip1), an inhibitor of the cyclin-dependent kinases, in both cultured cells and a transgenic mouse model." (PMID 21552502, 2011). "In accordance with previous reports, we found a ubiquitous expression of KLF6 either in normal and tumor tissues." (PMID 20126619, 2010). "In this regard, KLF6 sub-cellular distribution is mainly nuclear in normal tissues in contrast with an entirely cytoplasmic expression in the tumor counterpart." (PMID 20126619, 2010). "Expression and sub-cellular distribution of KLF6 was determined in normal and tumor tissues by using tissue microarrays and immunohistochemistry with two specific antibodies." (PMID 20126619, 2010).
tumor (continued). "We describe the domains that control KLF6 nucleo-cytoplasmic shuttling and how these domains play a role in KLF6 protein half-life and tumor suppressor function." (PMID 20844588, 2010). "Similar results showing nuclear and/or cytoplasmic distribution was observed for endogenous KLF6 in normal and tumor tissues by immunohistochemistry (; this work)." (PMID 20126619, 2010). "Current available information clearly demonstrates the involvement of KLF6 in the regulation of cell proliferation and apoptosis which can influence tumor development." (PMID 20126619, 2010). "Results clearly showed a specific and significant staining for KLF6 in both normal and tumor tissues with varied intensity." (PMID 20126619, 2010). "Next, the pattern of KLF6 protein was analyzed by immunohistochemistry assays in several normal and tumor tissue sections derived from paraffin-embedded samples spotted in an array." (PMID 20126619, 2010). "In this study we analyzed KLF6 expression and sub-cellular distribution by immunohistochemistry in several normal and tumor tissues in a microarray format representing fifteen human organs." (PMID 20126619, 2010). "Globally, KLF4 and KLF6 are considered as tumor suppressor gene, whereas KLF5 promotes cell proliferation." (PMID 20119532, 2009). "Further studies are needed to identify such cellular factors, for KLF6 to switch from a growth-inhibiting tumor suppressor to a growth-promoting oncogene." (PMID 20119532, 2009). "al (2021) reported the role of XIST in regulating immune cells, including macrophages, in the tumor microenvironment by the Xist/miR-101-3p/KLF6/C/EBPα, which might extend to NK cells through similar epigenetic and gene regulatory mechanisms." (PMID 40781182, 2025). "KLF6 regulates growth arrest and can function as a tumor suppressor." (PMID 38255985, 2024). "The Klf6 gene is a strongly validated target of murine miR-122 according to miRTarBase; its protein product, Krüppel-like factor 6, is a transcription factor pro-fibrogenic in the liver but also a tumor suppressor." (PMID 39684610, 2024). "KLF6 was a tumor suppressor and inhibited the progression of a variety of tumors." (PMID 38773440, 2024). "KLF6 was significantly and differentially expressed across multiple tumor types." (PMID 38773440, 2024). "KLF6 is a transcription factor with tumor-suppressive effects." (PMID 37405258, 2023). "Similarly to KLF2 and KLF3, KLF6 is another tumor suppressor whose levels are inhibited in PDAC tissues and whose overexpression reduces pancreatic cancer proliferation, migration, and invasion." (PMID 37239940, 2023). "KLF6 (p = 0.014) and SGMS2 (p = 0.031) were expressed more in tumor tissues compared to normal tissues, which suggested that KLF6 and SGMS2 might function as oncogenes in LUSC." (PMID 36056909, 2023). "Whether different tissue or tumor types engage different MAPK family members to regulate the same transcription factor (KLF6) remains to be examined." (PMID 37784093, 2023). "Moreover, the expression of miR-190a-3p and KLF6 were inversely correlated in CC tumor tissues (p < 0.001)." (PMID 35112985, 2022). "Accordingly, we wondered whether KLF6 was involved in the regulation of the suppressive effect of PGE2 on tumor miR-520d." (PMID 35664070, 2022). "As expected, silencing KLF6 enhanced tumor growth and shortened mouse survival." (PMID 35664070, 2022). "Interestingly, a KLF6-driven transcriptional network was identified to link lipid homeostasis and tumor growth in RCC." (PMID 35787628, 2022). "KLF6 was a target of miR-190a-3p and inhibited miR-190a-3p-induced CC tumor growth." (PMID 35112985, 2022). "The pro-tumor effect of ectopic UHRF1 was abolished by KLF6 overexpression." (PMID 35664070, 2022). "Compared to paired normal tissues, tumor tissues express low protein and mRNA levels of KLF6." (PMID 36615000, 2022). "Krüppel-like factor 6 (KLF6), a tumor suppressive gene, inhibits tumor growth and invasion in HCC." (PMID 35729523, 2022).